ENSG00000226773 (zinc finger pseudogene)
Gene: Processed pseudogene on chromosome 1 (92,203,148 to 92,203,991, forward strand). Ensembl gene ENSG00000226773.
Diseases named in the same sentence as ENSG00000226773 in open-access papers:
ENSG00000226773 is named in the same sentence as 1 disease in open-access papers, as found by Europe PMC text mining. Sharing a sentence is not in itself a finding about the gene and the disease.
ENSG00000226773 shares sentences with these, for which no sentence is quoted: myopia (1 paper).